EGFR (epidermal growth factor receptor)
Diseases named in the same sentence as EGFR in open-access papers (continued):
Sharing a sentence is not in itself a finding about the gene and the disease.
non-small cell lung carcinoma (continued). "Melosky discussed the treatment strategies for EGFR mutations in non-small cell lung cancer (NSCLC) and highlighted the existing EGFR mutations with an emphasis to first, second, and third lines of treatment plans in NSCLC." (PMID 33854965, 2021). "Currently, numerous studies have shown that EGFR is overexpressed or abnormally expressed in many different types of tumors, including in more than 80% of non-small cell lung cancers (NSCLC)." (PMID 34356665, 2021). "Epidermal growth factor tyrosine kinase inhibitors (EGFR-TKIs) are currently the most effective treatment for non-small cell lung cancer (NSCLC) patients, who carry primary EGFR mutations." (PMID 33562150, 2021). "Direct monitoring of T790M mutation in both CTCs and ctDNAs were employed to potentially guide treatment selection on EGFR-mutant non-small cell lung cancer (NSCLC) patients." (PMID 34512735, 2021). "The emergence of secondary resistance is the main failure cause of epidermal growth factor receptor-tyrosine kinase inhibitors (EGFR-TKIs) as a targeted therapy for non-small cell lung cancer (NSCLC)." (PMID 34054543, 2021). "Targeting NRP1, together with EGFR, attenuated the resistance to EGFR-targeted antibody treatment in non-small cell lung cancer." (PMID 32508529, 2020). "Epidermal growth factor receptor (EGFR) is a tyrosine kinase that is usually up-regulated in non-small cell lung cancer." (PMID 33346209, 2020). "Osimertinib is the first mutant-selective third-generation epidermal growth factor receptor (EGFR) tyrosine kinase inhibitor (TKI) that has been approved for patients with EGFR oncogene-addicted advanced non-small cell lung cancer (NSCLC)." (PMID 33374971, 2020). "EGFR is highly expressed in many cancers and amplified in 8.5% of solid tumors, including colorectal cancer (16.3%), non-small cell lung cancer (9%), genitourinary cancers (8.1%), and breast cancer (7.3%)." (PMID 33364187, 2020). "For example, in non-small cell lung cancer, E-cadherin was found to interact with epidermal growth factor receptor, playing a pivotal role in prognosis and progression." (PMID 33343628, 2020). "BIBW2992, also known as afatinib, is a potent EGFR inhibitor approved for the treatment of human non-small-cell lung cancer." (PMID 32482675, 2020). "For instance, lncFAM201 regulates the radiosensitivity of non-small cell lung cancer (NSCLC) by the EGFR/miR-370 axis." (PMID 31918742, 2020). "Although previously reported, little is known about choroidal metastasis in Epidermal Growth Factor Receptor (EGFR)-mutant Non-small cell lung cancer (NSCLC)." (PMID 33272243, 2020). "Efficacy and safety profiles of immune checkpoint inhibitors in EGFR-mutant non-small cell lung cancer patients." (PMID 33392095, 2020). "The aim of this study was to compare the EGFR mutations detected by ARMS PCR and SuperARMS PCR in cytology samples derived from advanced non-small cell lung cancer (NSCLC) patients." (PMID 32005253, 2020). "Previous studies provided evidence that elevated levels of USP25 are linked to the progression of different cancer types such as non-small-cell lung carcinoma (NSCLC), which are characterized by EGFR genetic alterations and aberrant EGFR signaling." (PMID 33202887, 2020). "For instance, EGFR T790M and C797S and ALK L1196M mutations are associated with resistance to EGFR tyrosine kinase inhibitor and ALK inhibitors in non-small cell lung cancer, respectively." (PMID 32099048, 2020). "The expression of MET and EGFR, both of which are coding genes of receptor tyrosine kinases, is positively correlated due to the regulation of microRNA in non-small-cell lung cancer and breast cancer." (PMID 33204717, 2020). "Epidermal growth factor receptor (EGFR) is a member of tyrosine kinases and is commonly overexpressed in some types of cancer, such as non-small-cell lung cancer, breast, esophageal, cervical, and head and neck cancer." (PMID 33096664, 2020).
non-small cell lung carcinoma (continued). "Our present findings indicate that, in several basal-like TNBC PDX models, YM155 is synergistic with afatinib, an EGFR inhibitor currently approved for the treatment of non-small cell lung cancer." (PMID 32001757, 2020). "IU is a feasible biomarker with potential benefit not only in the anti-EGFR therapy response assessment for non-small cell lung cancer but also in predicting the radio-chemotherapy outcome for cervical cancer." (PMID 33585186, 2020). "Multiple FDA approved drugs, such as Gefitinib and Lapatinib, are effective in EGFR-related non-small-cell lung cancer and several other cancers." (PMID 33424926, 2020). "Considering that overexpressed the epidermal growth factor receptor (EGFR) correlated closely with several non-small-cell lung carcinomas, the EGFR kinase was employed to be the target for the anti-proliferative activity of sardisterol against A549." (PMID 33143025, 2020). "Necitumumab is a human mAb used in chemotherapy combinations in the treatment of non-small cell lung cancer, and shows its effect by binding to the EGFR." (PMID 32421085, 2020). "The EGFR expression pattern in AML is controversial; two patients with AML and non-small cell lung cancer achieved remission of AML after the use of EGFR inhibitors, indicating that EGFR was the potential therapeutic target of AML." (PMID 32984037, 2020). "Targeting epidermal growth factor receptor (EGFR) through tyrosine kinase inhibitors (TKI) is a successful therapeutic strategy in non-small cell lung cancer." (PMID 33067539, 2020). "For this we used [11C]erlotinib, which is structurally identical to the epidermal growth factor receptor (EGFR)-targeting tyrosine kinase inhibitor erlotinib, a clinically used drug for the treatment of non-small cell lung cancer." (PMID 33153231, 2020). "In addition, according to the recent molecular-pathological profiling studies for advanced EGFR mutation-positive non-small cell lung cancer at baseline, the coexisting multiple genetic, phenotypic, and functional mechanisms may contribute to disease progression and cause intrinsic TKI resistance." (PMID 33370365, 2020). "The kinase targets in non-small cell lung cancer (NSCLC) include epidermal growth factor receptor (EGFR), anaplastic lymphoma kinase (ALK) and ROS proto-oncogene 1 (ROS1)." (PMID 32595510, 2020). "Gefitinib, a first-generation EGFR tyrosine kinase inhibitor (EGFR-TKI), is recommended for treatment of non-small cell lung cancer (NSCLC) patients who harbor activating EGFR mutations." (PMID 33193885, 2020). "Targeting of EGFR in the non-small cell lung cancer space has made incredible strides, with clear correlation between drug action, resistance mutations, and clinical activity." (PMID 33187135, 2020). "The Epidermal Growth Factor Receptor (EGFR) family of receptor tyrosine kinases (RTKs) is a major player in a variety of epithelial malignancies, such as breast cancer, non-small cell lung cancer, colorectal, gastric and ovarian cancer, and glioblastoma." (PMID 33228060, 2020). "Mitochondrial accumulation of epidermal growth factor receptor (EGFR), a receptor tyrosine kinase prevalently localized in the plasma membrane, has been shown to promote metastasis in non-small cell lung carcinomas and to be very high in stage IV." (PMID 33353059, 2020). "Abl in chronic myeloid leukemia (CML), ErbB2 in some breast cancers, and EGFR in some non-small cell lung cancer are a few examples of such mono-driver cancers." (PMID 32069833, 2020). "Epidermal growth factor receptor (EGFR) activation plays a pivotal role in EGFR-driven non-small cell lung cancer (NSCLC) and is considered as a key target of molecular targeted therapy." (PMID 33033232, 2020). "In contrast, in mouse embryonic fibroblasts, human embryonic kidney cells, and human A549 cells of non-small cell lung carcinoma, the fucosylation of EGFR is required for the binding of EGF and its subsequent signaling activity." (PMID 33238647, 2020).
non-small cell lung carcinoma (continued). "Osimertinib, a third-generation irreversible epidermal growth factor receptor (EGFR) tyrosine kinase inhibitor (TKI), has shown marked clinical benefit for non-small cell lung cancer (NSCLC) patients with EGFR activating mutations." (PMID 33374971, 2020). "In animal experiments, nebulization of the lungs has been achieved using magnetic nanoparticles (MNPs) with Epidermal growth factor receptor (EGFR), a commonly expressed protein in non-small cell lung cancer (NSCLC) cases as a target." (PMID 33173417, 2020). "Dacomitinib, a second-generation epidermal growth factor receptor (EGFR)-tyrosine kinase inhibitor, is a standard therapeutic option for patients with EGFR-mutant non-small cell lung cancer (NSCLC)." (PMID 33112047, 2020). "Overexpression of EGFR has been widely observed in many cancers including lung (especially non-small-cell lung carcinoma), colon, ovary, head and neck and breast cancers." (PMID 32521802, 2020). "This particular TargomiR, MesomiR 1, mimics miR-16, which is targeted to Epidermal Growth Factor (EGFR)-expressing cancer cells via an EGFR-bispecific antibody and shows success treating malignant pleural mesothelioma and non-small-cell lung cancer." (PMID 31936122, 2020). "In non-small cell lung cancer, a higher cumulative incidence of BM has been shown in EGFR-mutant cancer than in EGFR-wild type cancer." (PMID 31900168, 2020). "Treatment of xenografts derived from EGFR-mutant non-small-cell lung cancer (NSCLC) with cysteinase (an engineered enzyme that can deplete both cysteine and cystine with cell) showed increased ferroptosis." (PMID 33425217, 2020). "This study aimed to identify the influential factors for the sensitivity of epidermal growth factor receptor (EGFR) plasma test in non-small cell lung cancer (NSCLC)." (PMID 32746896, 2020). "In non-small cell lung cancer cells, it was observed that lupeol inhibits the phosphorylation of EGFR by binding to its tyrosine kinase domain and reducing STAT3 phosphorylation, which contributes to the induction of apoptosis." (PMID 32571387, 2020). "Cobas EGFR Mutation Test v2 (Roche Molecular Systems, Inc.)was approved on 1 June 2016 (FDA) for the detection of non-small cell lung cancer." (PMID 32774122, 2020). "Overexpression of wild-type EGFR is tumorigenic and denotes a therapeutic target in non-small cell lung cancer." (PMID 31896739, 2020). "The discovery of somatic mutations in the tyrosine kinase domain of the epidermal growth factor receptor (EGFR) drastically changed the therapeutic perspective of non-small-cell lung cancer (NSCLC)." (PMID 32983988, 2020). "The aberrant subcellular translocation and distribution of epidermal growth factor receptor (EGFR) represent a major yet currently underappreciated cancer development mechanism in non-small cell lung cancer (NSCLC)." (PMID 32321917, 2020). "Some studies indicated that EGFR tyrosine kinase (TK) inhibitor such as gefitinib, was useful for non-small cell lung cancer therapy in Japan in clinical trial phase II and III." (PMID 33680380, 2020). "Cetuximab is an EGFR-targeting chimeric mouse/human antibody approved for treatment of colorectal cancer, non-small cell lung cancer, and head and neck cancer." (PMID 33247180, 2020). "For example, combination of apigenin and gefitinib, an epidermal growth factor receptor (EGFR) inhibitor, to treat EGFR-resistant mutant non-small cell lung cancers impairs energy utilization and suppresses cell growth and malignant behavior." (PMID 33251216, 2020). "It is reported that relative abundance of mutant epidermal growth factor receptor (EGFR) can predict benefit from EGFR-tyrosine kinase inhibitors for advanced non-small-cell lung cancer." (PMID 33239043, 2020).
non-small cell lung carcinoma (continued). "EGFR-positive Non-small Cell Lung Cancer (NSCLC) is a dynamic entity and tumor progression and resistance to tyrosine kinase inhibitors (TKIs) arise from the accumulation, over time and across different disease sites, of subclonal genetic mutations." (PMID 33489892, 2020). "EGFR is a receptor of tyrosine kinase that is overexpressed in various types of cancer such, as breast, head and neck, ovarian and non-small cell lung cancer." (PMID 31983163, 2020). "Loss of E-cad stimulates EGFR-MEK/ERK signaling, which promotes invasion via the ZEB1/MMP2 axis in non-small cell lung cancer." (PMID 31952541, 2020). "For example, FGF-2-FGFR-1 activation through an autocrine loop was found as a mechanism of acquired resistance in non-small cell lung cancer (NSLC) to EGFR-tyrosine kinase inhibitor gefitinib." (PMID 32599808, 2020). "In non-small cell lung cancer (NSCLC), oncogenic driver mutations including those in KRAS and EGFR are typically mutually exclusive." (PMID 32130260, 2020). "Epidermal growth factor receptor- tyrosine kinase inhibitors (EGFR-TKIs) have shown promise against non-small cell lung cancers (NSCLCs) in clinics but the utility is often short-lived because of T790M mutations in EGFR that help evade TKIs’ action." (PMID 32641854, 2020). "A phase I clinical trial of dasatinib in combination with the EGFR inhibitor erlotinib in advanced non-small-cell lung cancer showed that the combination is tolerable with disease control in a subset of patients." (PMID 32370101, 2020). "Epidermal growth factor receptor (EGFR) tyrosine kinases inhibitors (TKIs) are effective therapies for non-small cell lung cancer (NSCLC) patients whose tumors harbor an EGFR activating mutation." (PMID 32438613, 2020). "Following high-dose EGFR-inhibitor treatment of non-small cell lung cancer (NSCLC) cell lines, a drug-tolerant “persister” population exhibiting reversible drug resistance can be consistently detected." (PMID 32365663, 2020). "In non-small cell lung cancer, for instance, MerTK participates in drug-resistance of epidermal growth factor receptor (EGFR) inhibitors." (PMID 32370748, 2020). "These therapies have been shown to improve survival in EGFR-positive cancers and have been approved for use in non-small-cell lung cancer, metastatic colorectal cancer, head and neck cancer, pancreatic cancer, and breast cancer." (PMID 32012988, 2020). "For example, EGFR/KRAS/ALK in non-small cell lung carcinoma, or BRAF, NRAS in melanoma, in agreement with the ESMO guidelines." (PMID 31787752, 2020). "Exon 19 deletions (Del19) and epidermal growth factor receptor (EGFR) exon 21 p.L858R mutations account for approximately 45% and 40% of the cases of epidermal growth factor receptor (EGFR) mutation-positive non-small-cell lung cancer (NSCLC)." (PMID 33036377, 2020). "Epidermal growth factor receptor (EGFR) tyrosine kinase inhibitors (TKIs) have been widely used to treat non-small cell lung cancer (NSCLC) because they inhibit tumour growth and metastasis." (PMID 31892990, 2020). "Combining existing and new treatments with EGFR-targeted therapy is a potential strategy in combating resistance to treatment in non-small-cell lung cancer." (PMID 32992872, 2020). "Patients with untreated stage IIIB/IV EGFR-mutant non-small cell lung cancer (NSCLC) were treated with pembrolizumab plus erlotinib." (PMID 33375183, 2020). "EGFR was overexpressed in many human cancers including ovarian, colorectal, and non-small-cell lung cancers." (PMID 32256661, 2020). "For example, in a cohort of EGFR-mutant advanced non-small-cell lung cancer (NSCLC) patients treated with erlotinib or gefitinib, the 8-week tumor growth rate has been shown to correlate with survival." (PMID 32321474, 2020). "EGFR-mutated non-small cell lung cancers are significantly less sensitive to ICI than wild-type EGFR-type non-small cell lung cancers and are more common in female than in male patients." (PMID 32708265, 2020).
non-small cell lung carcinoma (continued). "ctDNA analysis of epidermal growth factor receptor (EGFR) in non-small cell lung cancer (NSCLC) and v-Ki-ras2 kirsten rat sarcoma viral oncogene homolog (KRAS) in colorectal cancer (CRC) is well established." (PMID 32010431, 2020). "Low expression of programmed death-ligand 1 (PD-L1), epidermal growth factor receptor (EGFR) wild-type non-small cell lung cancer (NSCLCs) are refractory, and only few therapeutic options exist." (PMID 32899191, 2020). "The clinical efficacy of ICIs for non-small-cell lung cancer (NSCLC) patients harboring major mutations, such as EGFR or ALK mutations, is limited." (PMID 32283823, 2020). "This article appraises the key literature on the contemporary management of non-small cell lung cancer patients with acquired resistance to EGFR-TKIs, and envisions future directions in translational and clinical research." (PMID 32316715, 2020). "In a cohort of 84 non-small cell lung cancer patients, the combined use of exosomal-RNA and ctDNA sequencing improved the detection of EGFR (epidermal growth factor receptor)-activating mutations up to 98 vs. 84% for ctDNA alone." (PMID 33575258, 2020). "For example, EGFR-specific blocking antibodies (such as Erbitux and Vectibix) have been used to treat colorectal cancer, while EGFR inhibitors (like Iressa and Canmanna) have been used to treat non-small-cell lung cancer." (PMID 32695675, 2020). "Two groups have reported that patients who suffered from non-small-cell lung cancer (NSCLC) experienced an improvement in diabetes after erlotinib (an EGFR inhibitor) treatment." (PMID 33574751, 2020). "The two most common types of lung cancer brain metastasis (LCBM) are small-cell and non-small-cell lung cancer, the latter having three prominent mutations: KRAS, epidermal growth factor receptor (EGFR), and EML4-ALK." (PMID 32264860, 2020). "Similar findings were reported for diarrhea as an adverse effect of epidermal growth factor receptor–tyrosine kinase inhibitor (afatinib) for non-small cell lung cancer." (PMID 31691810, 2020). "In lung non-small cell lung cancer (NSCLC), the ctDNA determination of mutations of the epidermal growth factor receptor (EGFR) gene including the T790M-resistant allowed to selection the treatment between two drugs (erlotinib or osimertinib)." (PMID 32629823, 2020). "In patients with non-small cell lung cancers, high levels of EGFR protein expression or increased EGFR copy numbers derive greater therapeutic benefit from EGFR directed mAbs." (PMID 32012988, 2020). "EGFR inhibitors, like gefitinib and erlotinib, were found in non-small cell lung cancer (NSCLC) to reduce activation of Src and its substrates, suggesting the prominent role of Src in NSCLC progression." (PMID 32498343, 2020). "The study aimed to analyze the predictive and prognostic effects of platelet count on non-small cell lung cancer (NSCLC) patients treated with epidermal growth factor receptor tyrosine kinase inhibitors (EGFR-TKIs)." (PMID 33243184, 2020). "Erlotinib a first-generation EGFR TKI is currently approved for patients with non-small cell lung cancer and first line of treatment for metastatic or locally advanced pancreatic cancer in combination with gemcitabine." (PMID 32622356, 2020). "The development of specific therapies targeting driver alterations (e.g., EGFR mutations or ALK and ROS1 rearrangements) has changed the treatment paradigm and natural history of non-small cell lung cancer (NSCLC) harboring these aberrations." (PMID 30669267, 2019). "Recently, evaluation of non-small cell lung cancer samples reveals a positive correlation among EGFR activation, SCD1 Y55 phosphorylation and SCD1 protein expression." (PMID 30876460, 2019). "For exosomes from non-small cell lung cancer, epidermal growth factor receptor (EGFR), placental alkaline phosphatase (PLAP), and leucine-rich alpha-2-glycoprotein 1 (LRG1) proteins were among those found to be overexpressed." (PMID 31069333, 2019).